HIF1A (hypoxia inducible factor 1 subunit alpha)
Diseases named in the same sentence as HIF1A in open-access papers (continued):
Sharing a sentence is not in itself a finding about the gene and the disease.
infection (continued). "We demonstrate that a C. burnetii-infection initially induces HIF1α stabilization, which decreases then over the course of an infection." (PMID 35755850, 2022). "In this study, our results uncovered HIF-1α as a virus-dependent host factor important for optimal infection of macrophages by PRRSV, suggesting a potential new anti-PRRSV target." (PMID 36416550, 2022). "The frequencies of CD4, CD8 and DN T cells in lungs from Hif1a cKO and WT mice before or after infection with M. tuberculosis were instead similar." (PMID 36064840, 2022). "On the other hand, it has been described that infection of gastric cells with H. pylori increases the levels of HIF-1α." (PMID 36313672, 2022). "There was a marked upregulation of HIF-1α mRNA in MC3T3-E1 cells at 7 days after infection with S. aureus." (PMID 35852344, 2022). "The infection of BMM with virulent M. tuberculosis also increased the levels of HIF-1α mRNA and protein expression." (PMID 36121152, 2022). "We recently showed that HIF1α is responsible for controlling C. burnetii infection in an in vitro infection model using primary murine and human macrophages." (PMID 35755850, 2022). "This IFN-γ-independent control of infection requires activation of the transcription factor HIF-1α and a shift to aerobic glycolysis in infected macrophages." (PMID 35877763, 2022). "In contrast, recombinant GM-CSF controls infection in peritoneal macrophages, induces lipid droplet biogenesis, and also requires HIF-1α for control." (PMID 35877763, 2022). "GW6471 was found to inhibit the hypoxia inducible factor 1 subunit alpha (HIF1α) pathway when hPSC-AOs or hPSC-COs were treated after infection." (PMID 34850919, 2022). "Areas of intense positivity, suggestive of HIF-1a accumulation, were predominantly seen in and around blood vessels, which extended into the brain parenchyma in infection." (PMID 35365631, 2022). "Elevated HIF-1α in macrophages also resists infection, which are able to kill and clear pathogens, such as mycobacterium tuberculosis, severe acute respiratory syndrome coronavirus 2 (SARS-CoV-2), and some fungi." (PMID 36761171, 2022). "Validation using quantitative RT-PCR analysis confirmed that the expression of HIF-1α was significantly upregulated in L. biflexa-infected BMDMs compared to in uninfected BMDMs (P < 0.005 for 2-h infection; P < 0.05 for 24-h infection)." (PMID 35638785, 2022). "During infection with pathogens, HIF-1α expression is increased in Th2 cells, leading to Th2 cells proliferation." (PMID 36761171, 2022). "HIF-1α was expressed in HIV-1 infected primary CD4+ T cells in higher levels than mock infected cells 48 hours post infection." (PMID 36467738, 2022). "While DMOG increased both HIF-1α-specific targets Nos2 and Pgk1 in LysMCreARNTf/+ macrophages compared to untreated cells during infection, this effect was only significant for Nos2 expression." (PMID 34959539, 2021). "This indicates facilitated bacterial translocation from the primary infection site to the blood in HIF-1α KO mice despite the more rapid wound healing." (PMID 34349124, 2021). "Intriguingly, MFN2-mediated HIF-1α activation is augmented by mitochondrial respiratory chain complex I and ROS and contributes to macrophage-mediated inflammatory responses during infection." (PMID 34482801, 2021). "In particular, we found that the lungs of CftrF508del mice had increased mRNA levels of Hif1α, both basally and after infection with conidia, compared to wild-type mice." (PMID 34835243, 2021). "HIF-1α stabilization reduces oxidative phosphorylation and increases glycolysis during infection with B. abortus and, likewise, enhances nitric oxide production, inflammasome activation and IL-1β release in infected macrophages." (PMID 33989349, 2021). "Altogether, these findings already suggest that HIF1α is not only required for the cellular adaptation to hypoxia, but also for the immune response to infection under normoxic conditions." (PMID 33125509, 2021).
infection (continued). "Since patients experiencing virologic failure exhibit productive infection, it is conceivable that the increased expression of HIF-1α was driven by factors other than intracellular hypoxia." (PMID 34837007, 2021). "Further research is required to understand the different effect of HIF1α and/or hypoxia on autophagy in the different infection models." (PMID 33125509, 2021). "HIF1α not only prevents immuno-pathology during infection, but also protects against M. marinum infection by inducing the pro-inflammatory cytokine IL-1β." (PMID 33125509, 2021). "Myeloid, but not neutrophil, HIF1α-deficient mice had increased bacterial loads in the lungs and distant organs after infection as compared to control mice, pointing at a role for HIF1α in macrophages." (PMID 34393650, 2021). "Taken together, these results indicate that HIF-1α contributes to the induction of M1-like macrophages during the early phase of the infection." (PMID 33989349, 2021). "In the context of infection, HIF1α can be induced due to the hypoxic environment of inflamed tissue and through stimulation of cells with bacterial components." (PMID 34393650, 2021). "Interleukin (IL)-1β, another HIF-1α regulated molecule, has been shown to control the outcome of infection with T. b." (PMID 34587172, 2021). "It has been revealed that the rise in ImpL2 expression in plasmatocytes is dependent on HIF1α activity in these cells upon infection." (PMID 33659253, 2021). "As HIF-1α promotes SARS-CoV-2 replication and is induced upon the infection of several viruses, thus, we determined the effect of HIF-1α on the infection of other viruses." (PMID 34408131, 2021). "In cells transfected with the scramble siRNA, infection with LF82 induced HIF-1α expression and autophagy, as shown by the increased LC3-II level." (PMID 33805299, 2021). "To test NK cell-mediated control of bacterial infections, we introduced the GAS inoculum subcutaneously into the shaved back skin of WT and HIF-1α KO littermates and followed progression of the infection over four days." (PMID 34349124, 2021). "Together, these results indicate that the HIF-1α pathway influences the inflammatory/glycolytic profile that occurs in macrophages upon infection with B. abortus." (PMID 33989349, 2021). "This protects from infection, as MC exhibit increased microbicidal activity and more efficient control of invasive bacterial infection, when HIF1α is increased." (PMID 33815383, 2021). "This strongly suggest a role for KSHV in the negative regulation of HIF1α on infection of human cells in hypoxic conditions." (PMID 34279223, 2021). "Our results indicate that infection of S. Typhimurium leads to increased HIF-1α expression in the colon, which was significantly reduced upon Gefitinib and Acriflavin treatment." (PMID 33868285, 2021). "In zebrafish infection models using Mycobacterium marinum, HIF-1α stabilization enhances IL-1β expression, and helps clear infections via activating neutrophils." (PMID 33718271, 2021). "Our data demonstrate the critical role of HIF-1α in shaping appropriate TCA cycle activity in response to infection and highlight the consequences of a dysregulated immunometabolic response." (PMID 34749531, 2021). "Infection efficiency was similar in HIF1A shRNA- or scrambled shRNA- infected cells, based on expression of the GFP reporter." (PMID 34470658, 2021). "Other studies demonstrated that HIF-1α supports the clearance of bacterial infections in mouse keratinocytes infected with Group A streptococci, a Mycobacterium marinum zebrafish model or infection of murine bladders with uropathogenic Escherichia coli." (PMID 34149713, 2021). "The influenza H1N1 virus has been found to exploit this mechanism, mimicking the hypoxic response to stabilize HIF-1α during infection of airway epithelial cells." (PMID 33868294, 2021).
infection (continued). "Our data show that hypoxia-inducible factor-1 (Hif-1a) is significantly increased, whereas peroxisome proliferator activated receptor gamma (Pparg) is significantly decreased, following infection with the organism." (PMID 34066663, 2021). "On the opposite, HIF-1α cannot be effectively transcribed in infection or inflammation when NF-κB gene is deleted." (PMID 33763034, 2021). "For instance, in a model of progressive pulmonary tuberculosis in BALB/c mice, the blockage of HIF1α worsened the disease during the early phase of infection, while it decreased bacterial load during late tuberculosis." (PMID 33125509, 2021). "Because of the relevance of these interactions, several viruses attack this pathway as a strategy to induce HIF-1α upon infection." (PMID 34360716, 2021). "Taken together, these data strongly suggest that MFN2-mediated induction of HIF-1α is essential for the activation of inflammatory signaling in macrophages during infection." (PMID 33972668, 2021). "During wound healing and infection in the skin there is a hypoxic environment involving HIF-1α and NK cells." (PMID 34349124, 2021). "HIF1α, which is a key regulator of transcriptional signaling in hypoxic conditions, was induced following infection with either virus, as were HSP90B1 and DBF4, which are mediators of the unfolded protein response and cell cycle arrest, respectively." (PMID 33405202, 2021). "RNA sequencing on bacterial skin lesions from WT and HIF-1α KO mice at day 2 post infection uncovered the downregulation of genes involved in the coordination of leucocyte responses, including chemotaxis and cytokine signalling." (PMID 34349124, 2021). "The infection of several cell lines with NDV inhibits HIF-1α protein accumulation and, consequently, decreases the transcription of the HIF-1α target genes, particularly the carbonic anhydrase 9 gene, which encodes the CAIX protein." (PMID 33135539, 2020). "Previous studies with RSV using human bronchial epithelial cells (HBECs) and an experimental mouse model have demonstrated the stabilization of HIF-1α following infection, in part through RSV-induced nitric oxide-dependent pathways." (PMID 32993138, 2020). "We have previously reported that HIF-1α activation is a general phenomenon in infections with subsequent VEGF secretion." (PMID 32529267, 2020). "More importantly, HIF-1α is a critical hub that integrates hypoxic and immunogenic signals during infection and/or inflammation." (PMID 33424870, 2020). "It has already been shown in H. capsulatum that modulation of HIF-1α can have a positive effect on the clearance of infection in MΦ." (PMID 32977563, 2020). "For instance, infection with viruses such as hepatitis C or hepatitis B can promote processes that induce oxidative stress in the cell, influencing the stability of HIF-1α after infection." (PMID 33135539, 2020). "Several studies show the downstream stimulation of HIF-1α, either by hypoxia or infection, as well as the exposure to nitric oxide (NO)." (PMID 32977563, 2020). "To better understand the influence of HIF-1α on PGD expression in GIST cells, we downregulated HIF-1α expression in GIST-T1R and GIST-882R cells by lentivirus infection and verified the altered expression of HIF-1α in these GIST cell lines by western blotting." (PMID 32719331, 2020). "Pathogens such as influenza virus, vaccinia virus (VACV), Epstein-Barr virus (EBV) and hepatitis B virus (HBV) have been shown to stabilize HIF1α after infection to stimulate the transcription of hypoxia inducible genes, even under normoxic conditions." (PMID 32718318, 2020). "In all mock-infected controls, exposure to hypoxia led to the robust accumulation of HIF-1α in DLD-1 cells, while the infection of hypoxic cells with EnAd resulted in decreased expression levels of HIF-1α and its target CAIX." (PMID 32244697, 2020).
infection (continued). "Noteworthy, most viruses studied to date have been shown to positively modulate this pathway by upregulating the stabilization of HIF-1α as a consequence of infection." (PMID 33135539, 2020). "Hypoxia-inducible factor-1α (HIF-1α) has been shown to be important for priming of the innate immune system via cathelicidin antimicrobial peptide LL-37 during infections with Candida albicans." (PMID 32977563, 2020). "EnAd infection significantly decreased HIF-1α mRNA expression in hypoxia and normoxia, which correlated with decreased GLUT1 and VEGF mRNA expression compared to mock-infected controls at 24 h post-infection." (PMID 32244697, 2020). "Though there is only little data on the role of HIF-1α as part of the antifungal host response during infection with other fungi, HIF-1α also has been shown to interact with autophagy in various other challenges, and to play a role in apoptosis." (PMID 32977563, 2020). "HIF1α-mediated induction of aerobic glycolysis is integral to the host macrophage response during infection with Mtb, as this promotes bacillary clearance." (PMID 32477344, 2020). "Infection of brain ECs with S. pneumoniae followed by HIF-1α/VEGF expression and EC permeability was assessed in vitro." (PMID 32529267, 2020). "At eight hours post-infection, the HIF-1α and VEGF mRNA levels in infected cells were comparable to mock controls, while EnAd infection significantly induced the mRNA expression of HIF-2α and reduced the levels of GLUT1 mRNA compared to mock-infected cells." (PMID 32244697, 2020). "Given that VEGF is a known permeability factor targeting junctions in the paracellular pathway, we next tested if infection-induced HIF-1α/VEGF is required for bacterial transmigration and permeability at the BBB." (PMID 32529267, 2020). "Glycolytic activation through the hypoxia-inducible factor-1α (HIF-1α) pathway was required for differentiation to the M1 phenotype, which conferred protection against infection." (PMID 32596169, 2020). "Hypoxia-inducible factor 1 α (HIF-1α) is involved in cell proliferation, tumor angiogenesis, apoptosis, infection, inflammatory diseases, and innate immune responses." (PMID 33376580, 2020). "Collectively, the data show that HIF-1α regulates a number of key functions of innate cells for them to control infections." (PMID 32977563, 2020). "Our findings indicate that following the onset of infection (4 h after bacterial challenge) WT BM neutrophils displayed high generation of ROS, elevated levels of HIF-1α+ neutrophils as well as lactate production and release (respectively)." (PMID 32669546, 2020). "The regulation of Ldh expression by Hif1α in activated immune cells was verified by knocking down Hif1α expression in macrophages 24 hr before infection (Hml >Hif1α[RNAi])." (PMID 31609200, 2019). "During infection, chemically enhanced HIF-1α abrogated mitochondrial respiration and diminished glycolysis." (PMID 31036602, 2019). "Our objective was to achieve the deletion of exon 2 in HIF1α locus in tissues by infection with an MHV68-Cre virus." (PMID 31809522, 2019). "Genes related to resistance to infection, cytotoxicity, cell death, and G protein-coupled receptor signaling such as c3ar1, hif1α, il22, and ifnγ were highly expressed in mice colonized with P. aeruginosa PA14 WT." (PMID 30867416, 2019). "The protein level of EZH2 was enhanced in p-SLC34A2 group, while si-HIF-1α infection resulted in EZH2 expression significantly declined in p-SLC34A2 group." (PMID 30038060, 2019). "Mt infection of murine lung tissue leads to increased levels of HIF-1α within MPs and T-cells present in granulomatous lesions." (PMID 30886834, 2019). "HIF-1α stabilization was detected in peripheral blood monocyte-derived macrophages at 2 to 24 h after infection with viable yeast cells." (PMID 31036602, 2019). "Homozygous deletion of HIF1α is lethal for development through embryogenesis, we utilized Cre-LoxP strategy to generate HIF1α deletion during MHV68-Cre infection." (PMID 31809522, 2019).
infection (continued). "Levels of mRNA expression of some MHV68 HRE-containing genes were modestly increased during wild-type infection at 3% O2 of HIF1α WT cells." (PMID 31809522, 2019). "Using a well-established zebrafish M. marinum model of TB, we show that manipulation of Hif-1α can stimulate this proinflammatory network, aiding the host fight against infection and moving toward early clearance of infection." (PMID 30552162, 2019). "We found that the upregulation of glycolytic enzymes by MHV68 during normoxic infection was impaired by HIF1α deletion." (PMID 31809522, 2019). "First, 3T12 cells were transfected with a HIF1α siRNA for 24 hours, followed by infection in normoxic conditions." (PMID 31809522, 2019). "In a previous study, we showed that infection of gastric cells with H. pylori induces HIF-1α protein levels, which in turn coincided with a decrease in Cyclin D1 half-life and alterations in the cell cycle." (PMID 31185594, 2019). "The quantity of HIF-1α induced by infection was elevated by hypoxia or a chemical HIF-1α stabilizer in MDM." (PMID 31036602, 2019). "marinum model of TB that the initial immune response to infection can be enhanced by stabilizing host-derived hypoxia-inducible factor-1 α (Hif-1α), leading to reduced bacterial burden." (PMID 30552162, 2019). "We conclude that inhibition of HIF1α activity during acute MHV68 infection impairs virus expansion in the initial days of infection." (PMID 31809522, 2019). "The hypoxia-inducible factor 1 alpha (HIF1α) protein and the hypoxic microenvironment are critical for infection and pathogenesis by the oncogenic gammaherpesviruses (γHV), Kaposi sarcoma herpes virus (KSHV) and Epstein-Barr virus (EBV)." (PMID 31809522, 2019). "Following this characterization, the ability to induce HIF-1α protein levels in AGS cells was tested after 8 h of infection." (PMID 31185594, 2019). "Infection of floxed transgenic mice with MHV68-Cre to knock-out HIF1α in vivo revealed that HIF1α is necessary for optimal viral expansion on the site of acute infection in the animal model." (PMID 31809522, 2019). "In order to characterize the biological relevance of augmented HIF-1α protein during infection, we elucidated its impact on fungal survival." (PMID 31036602, 2019). "By 72 hr post infection, 25% of Hml >Hif1α[RNAi] flies died compared to 7% of controls, and the medium time to death (MTD) in Hml >Hif1α[RNAi] flies was 10 days compared to 23 days in controls." (PMID 31609200, 2019). "At sites of tissue damage and infection, both inflammation and decreased oxygen availability result in HIF-1α stabilization and its nuclear translocation." (PMID 31681292, 2019). "As a first approach, we employed the MHV68-Cre infection of primary MEFs from the HIF1αLoxP mouse strain to address the consequences of HIF1α deletion in lytic infection." (PMID 31809522, 2019). "In Mm infected ZF, HIF-1α stabilization induced IL-1β production by MPs and increased neutrophil NO production that is protective against infection." (PMID 30915076, 2019). "Taken together, these data demonstrate induction of HIF-1α protein accumulation by infection with H. capsulatum in MDM, which can be further enhanced by hypoxia or a chemical stabilizer." (PMID 31036602, 2019). "Both Hif1α and Ldh are necessary for the full development of infection-induced changes in systemic carbohydrate metabolism and for resistance to bacterial infection." (PMID 31609200, 2019). "The Hif1α silencing completely suppressed the infection-induced changes in carbohydrate metabolism, but infected Hml >Ldh[RNAi] flies still significantly increased circulating glucose, albeit to a lesser extent than in the infected controls." (PMID 31609200, 2019). "We report that MHV68 infection of permissive cells upregulated HIF1α transcription and led to the upregulation of its protein levels." (PMID 31809522, 2019).